CSF1 (colony stimulating factor 1)
Diseases named in the same sentence as CSF1 in open-access papers (continued):
Sharing a sentence is not in itself a finding about the gene and the disease.
tumor (continued). "A key observation is that stimulating macrophages by CSF-1 and tumor cells by EGF induce podosomes and invadopodia formation, respectively, which can mediate basement membrane and tissue invasion of tumor cells." (PMID 39003350, 2024). "Like LRG1, CSF1 is also important in regulating redundant inflammation in the tumor microenvironment and in achieving timely wound healing after chemical and physical insult." (PMID 38386171, 2024). "Overexpression of CSF-1 and CSF-1R on M2 macrophages represents a significant factor contributing to adverse tumor prognosis." (PMID 38646440, 2024). "The critical role of macrophages in ID8 tumor has been described using a colony-stimulating factor 1 (CSF-1) receptor kinase inhibitor." (PMID 39612052, 2024). "For HRP tumors, we proposed activating bystander T cells by tumor vaccines or cytokine therapies and targeting M2 macrophages by anti‐CSF1/CSF1R antibodies." (PMID 39136172, 2024). "Pharmacological inhibition of colony-stimulating factor 1 (CSF-1)/CSF-1R axis inhibited TAMs and impaired tumor progression." (PMID 38542388, 2024). "EGF also stimulates CSF-1 secretion by cancer cells, forming a positive feedback loop between macrophages and tumor cells." (PMID 39003350, 2024). "CSF-1 (M-CSF) and IL34 were determined to be expressed by the malignant cell population and other tumor-associated cells." (PMID 39272914, 2024). "CSF1 secreted by tumor cells both recruits macrophages to the tumor microenvironment and promotes macrophage expression of EGF." (PMID 39555068, 2024). "We applied quantitative PCR to determine the expression of 14 genes including CXCR2, SAA, COX1 and COX2, PPAR-α, -δ and -γ, Gro-α and -γ, IL8, p21, c-myc, CD44 and CSF1 in tumor and adjacent normal mucosa of 21 CRC patients." (PMID 38891062, 2024). "TAMs promote angiogenesis by secreting VEGF, induce Treg differentiation through IL-10 and TGF-β secretion, and are recruited to tumor sites by tumor-derived CSF-1." (PMID 39770505, 2024). "The inhibitors targeting HIF-1α also can inactivate the tumour microenvironment-derived extrinsic signals (CSF1 and CCL5) to further improve the response of targeting intrinsic molecular pathways to overcome the resistance to anti-VEGF therapy." (PMID 39267775, 2024). "This paracrine cycle between macrophages and cancer cells is mediated by EGF, and CSF-1 promotes tumor invasion." (PMID 38787372, 2024). "Upregulation of CSF-1 in tumor cells following exposure to paclitaxel was correlated with high TAM infiltration, and the recruited TAMs suppressed paclitaxel-induced mitotic arrest in breast tumor cells." (PMID 39003350, 2024). "Expression analysis by qPCR, using human-specific primers, showed a significant increase in the expression of some chemoattractant factors (i.e., CCL2 and CSF1) of the cell-cycle inhibitor P21 in the tumor cells of PTP4A2-KO xenografts." (PMID 38904264, 2024). "Tumor cells secrete CSF-1, which binds to CSF1R on macrophages, initiating downstream pathways to recruit and polarize TAMs." (PMID 38273373, 2024). "Tumor cells can release cytokines like CSF1, IL-34, and VEGFA to induce metabolic reprogramming and phenotypic transition in TAMs like M2-like polarization." (PMID 38714539, 2024). "In vivo, CSF1KD mice exhibited reduced osteolytic activity, likely induced by CSF-1 produced by tumor cells, as well as decreased CSCs and osteoclastogenesis, thereby blunting tumor progression." (PMID 39457693, 2024). "Under the combined influence of hypoxia and cytokines, such as CCL2, CCL5 and CSF1–-produced by tumor cells, fibroblasts, endothelial cells, or TAMs themselves, macrophages will be largely recruited to hypoxic tumor compartments." (PMID 39175095, 2024). "Collectively, these findings underscore the critical role of CAFs and the CSF-1/CSF-1R axis in tumor progression and immune modulation within the TME and suggest potential therapeutic strategies aimed at enhancing anti-tumor immune responses." (PMID 39457693, 2024).
tumor (continued). "Data showed that injection of CSF-1-depleted cancer cells in mice reduced tumor mass and osteolytic bone metastases compared to controls, as well as the percentage of Ki-67-positive tumor cells." (PMID 38254773, 2024). "Monocytes are recruited from the peripheral circulation to the TME through colony-stimulating factor-1 (CSF-1) secreted by tumor cells, and subsequently differentiate into macrophages." (PMID 39144141, 2024). "The recruitment of macrophages and myeloid cells into the tumor microenvironment can be prevented through the inhibition of CCL2/C–C chemokine receptor type 2 or CSF1/CSF1-R." (PMID 39682696, 2024). "Overall, these data suggest that increased expression of CSF-1 in EBV-associated tumour cell CM can upregulate CCR5 receptor expression on monocytes and migration towards increased CCL5 in EBV-associated tumour cell CM." (PMID 39267775, 2024). "Targeting the CSF1/CSF1R axis in combination with chemotherapy decreased tumor burden and increased overall survival of mice." (PMID 39682696, 2024). "Nevertheless, when the tumor grows, the tumor cells repolarize to M2-type TAMs by a variety of pathways, including the production of cytokines including CSF-1, IL-4, and IL-10, lactate secretion, nutrient shortage, and hypoxia." (PMID 38185636, 2024). "Tumor endothelial cells secrete IL-6 and CSF-1 which promote anti-tumor alternative macrophage polarization by triggering Akt1/mTOR pathway, resulting in anti-inflammatory and pro-tumorigenic macrophage activation." (PMID 38576482, 2024). "Blockade of CSF-1-CSF-1 R can functionally reprogramme macrophage responses, enhancing their antigen-presenting abilities to produce anti-tumor T cell responses." (PMID 38533720, 2024). "A paracrine EGFR/CSF-1R interaction exists between TAMs and tumor cells in which CSF-1 stimulates macrophages to release EGF, leading to tumor cell proliferation and migration." (PMID 39003350, 2024). "CSF-1, also known as M-CSF, is a key proliferation and differentiation factor for monocyte–macrophage lineages that recruits macrophages to the tumor site and promotes TAM polarization." (PMID 38787372, 2024). "CSF1, a myeloid cytokine released during infection and inflammation, facilitates the recruitment of MDMs to the tumor bed and polarizes them to an M2-like phenotype." (PMID 39068459, 2024). "EGF and CSF1 induce the formation of invadopodia in tumor cells and podosomes in TAMs, structures that break the ECM and facilitate intravasation." (PMID 39003350, 2024). "In fact, blocking the CSF-1/CSF-1R axis results in a decrease in CD4+ Foxp3+ Tregs correlated with a reduction in tumor growth and enhances CD8+ T cell-mediated immunity in the sarcoma TME." (PMID 39457693, 2024). "Inhibiting factors such as colony-stimulating factor-1 (CSF-1) or its receptor, CSF-1R, have shown promise in preclinical models, leading to reduced tumor growth and prolonged survival." (PMID 38732975, 2024). "These cells have a high degree of plasticity and can adopt an immune phenotype similar to M2 macrophages when stimulated by colony-stimulating factor 1 released by tumor cells." (PMID 38255288, 2024). "In this setting, PTPN11 inhibition induced a shift in tumour microenvironment (TME) myeloid cell populations towards an inflammatory, anti-tumour phenotype, in part via effects on colony-stimulating factor 1 (CSF1) signalling pathways." (PMID 38334623, 2024). "Inhibitors of CSF1 signaling have been tested in combination with abiraterone demonstrating that TAM blockade in this setting disrupted tumor promotion and maintained a more durable therapeutic response compared to abiraterone alone." (PMID 39635522, 2024). "An in vitro assay demonstrated the involvement of the CSF-1/CSF-1R axis in tumor migration via anoikis resistance and the induction of pro-angiogenic factor expression, such as VEGFA, in GC tissues." (PMID 38254773, 2024).
tumor (continued). "Tumor cells secrete CSF-1 and TAMs secrete epidermal growth factor (EGF) to enable both cell types to co-migrate along collagen fibers in an alternating fashion." (PMID 39588367, 2024). "We underlined the value of CAFs in regulating tumor-promotion functions of myeloid cells through the production of MIF, CSF1, CXCL12, and FN1." (PMID 39323622, 2024). "Inhibitors targeting the CCL2/CCR2 or CSF-1/CSF-1R signaling axis have shown promise in reducing macrophage accumulation at tumor sites." (PMID 39146202, 2024). "CSF − 1R is a transmembrane tyrosine kinase receptor, and the binding of CSF-1 to CSF-1R on the cell surface exerts pro-tumor effects." (PMID 38303927, 2024). "Tumor cells expressing colony-stimulating factor-1 [CSF-1] bind to the CSF-1 receptors [CSF-1Rs] on macrophages in the tumor microenvironment to facilitate tumor invasion." (PMID 39064514, 2024). "CSF-1 exhibits both autocrine and paracrine effects within the tumor milieu, underscoring its involvement in tumor growth." (PMID 39457618, 2024). "It has been found that proliferation, recruitment, differentiation from a tumoricidal to a tumor-promoting phenotype, and survival of macrophages depend on CSF-1/CSF-1R axis." (PMID 39003350, 2024). "CSF-1, derived from fibroblasts, tumor cells, etc., is produced in membrane-bound form, secreted glycoproteins and proteoglycans." (PMID 39416792, 2024). "Pretreatment tumor tissue samples from a total of 44 patients were evaluated via immunohistochemistry for CSF-1 and CD163." (PMID 39734810, 2024). "According to this study, LMS tumor cells secreted CSF-1 that, in turn, induced macrophage recruitment at the tumor sites." (PMID 38254773, 2024). "Monocytes are recruited in to the tumor site and differentiate into macrophages upon tissue infiltration, and this process is mediated by inflammatory signals such as CCL2, CCL5, and CSF-1 secreted by tumor cells and other cells within the malignant TME." (PMID 38730724, 2024). "One such mechanism involves the release of CSF-1 from tumor cells attracting monocytes to the tumor environment, and the activation of EGF signaling promoting the migration of tumor cells." (PMID 37108109, 2023). "CSF-1 is also responsible for recruiting myeloid-derived suppressor cells (MDSCs) to the tumor microenvironment, where it can then drive tumor progression through suppression of antitumor immune responses and promotion of angiogenesis." (PMID 36980578, 2023). "CSF-1 activation in dt-TGCT leads to recruitment of CSF-1R+ macrophages which make up a large bulk of the tumor mass." (PMID 37114134, 2023). "Whereas, M2 TAM is immunosuppressive, contributes to tumor growth, and requires M-CSF (CSF1) and anti-inflammatory stimuli (e.g., IL-4) for generation." (PMID 36922564, 2023). "Targeting both CCL2/CCR2 and CSF-1/CSF-1R axis is therefore relevant to a tumor that overexpresses M-CSF, CCL2 and other chemokines that bind to CCR2 such as CCL7." (PMID 38076998, 2023). "Radiation can cause tumor cells to release chemokines and growth factors, such as CCL2, CCL7, and CSF-1, that are important for MDSC recruitment in the TME." (PMID 37208386, 2023). "CSF-1 produced by tumor cells interacts with CSF-1R, which undergoes autophosphorylation, triggers downstream signaling and determines macrophage differentiation." (PMID 37810971, 2023). "Macrophages and tumor cells participate in a cross-communication paracrine loop in which TAMs express EGF which signals on tumor cells, while reciprocally tumor cells express CSF1 which promotes macrophage chemotaxis, differentiation, and survival." (PMID 37199172, 2023).
tumor (continued). "In most tumor cells there was 1 copy of the normal gene (fused green and orange signal giving orange‐red color), and multiple green signals signifying duplicated CSF1 3' end with deletion of the 5' end in the other chromosome." (PMID 37305870, 2023). "Macrophage can be recruited to the tumor periphery by CSF-1 produced by CRC cells, and further secret factors to promote cell invasion." (PMID 36647017, 2023). "Higher levels of CSF-1 in SM and EC users suggests that there is a shared pathway in both atherosclerotic and cancer pathways, potentially fostering tumor growth." (PMID 37374908, 2023). "The results showed that the expression patterns of SPP1 and CSF1 in normal and tumor tissues were most similar to those of ITGAV and PLAUR, respectively." (PMID 37097499, 2023). "Irradiation also stimulates DNA damage-induced kinase ABL1 mediated upregulation of macrophage colony-stimulating factor (M-CSF or CSF1) in tumor cells." (PMID 37377970, 2023). "SRC is related to tumor suppressor factors, monocyte-macrophages and T cell chemokines by interacting with IL-15, colony stimulating factor 1 (CSF1), C-C motif chemokine ligand 5 (CCL-5), etc.." (PMID 36902024, 2023). "SLC7A11 upregulation promotes HIF-1α expression by reducing α-ketoglutarate (αKG) levels, which in turn promotes the expression of programmed death ligand 1 (PD-L1) and CSF1 in tumor cells." (PMID 37663266, 2023). "The M2 macrophages migrate towards nearby blood vessels, up spatial gradients in CXCL12, and the CSF-1/EGF paracrine loop enables tumour cells to trail behind them." (PMID 36972297, 2023). "The use of an RNA interference strategy to inhibit the expression of CSF1R or CSF1 also affected tumor growth in both xenograft and GEM models of cancers." (PMID 37108657, 2023). "The administration of CSF1/CSF-1R inhibitors to blockage MDSCs was an effective monotherapy for tumor control and adjuvant therapy to overcome treatment resistance." (PMID 37886177, 2023). "Recruitment of TAMs to tumor sites is mediated by tumor-derived proteins (e.g. CSF-1, VEGF and chemokines)." (PMID 37637050, 2023). "We first screened a panel of murine carcinoma cell lines to assess the production of tumor-CSF1 in vitro." (PMID 37505292, 2023). "High levels of CSF1 within the tumor microenvironment have been shown to recruit and reeducate macrophages to produce factors that promote tumor invasiveness and accelerate metastasis." (PMID 37505292, 2023). "CSF plays a paramount role in TAM recruitment and survival, and therefore, blockading of the CSF1/CSF1R axis can reduce monocyte recruitment to the tumor site and its differentiation while further hampering the survivability of the existing TAMs." (PMID 38035101, 2023). "In response to tumor-derived CSF1, immunosuppressive M2 macrophages undergo active polarization and recruitment to the TME." (PMID 37504287, 2023). "Numbers of circulating tumor cells and metastases were shown to be reduced by genetic ablation of Csf1, a major growth factor required for macrophage differentiation." (PMID 37005447, 2023). "We next harvested tumors from animals bearing either 4T1 parental or CSF1−/− tumors to assess the impact of CSF1 knockout within the tumor microenvironment." (PMID 37505292, 2023). "Tumor cells secrete a cytokine mixture containing TGFβ1, which acts as a strong immunosuppressant by blocking the maturation of monocytes through its CSF-1 (colony-stimulating factor 1) content." (PMID 37108109, 2023). "It is noteworthy that cytokines such as CCL2, CCL5, and CSF1 were found to be involved in the attraction of MDSCs to the tumor site." (PMID 37033447, 2023).
tumor (continued). "Subsequent investigation has elucidated that EGF secreted by TAMs engages with CSF1 released by tumor cells facilitating the migratory capabilities of the tumor cells." (PMID 38035101, 2023). "Recently, CREBBP LOF has also been proposed to increase the expression of CSF1 and CCL2 in DLBCL tumor cells, thereby promoting tumor-associated macrophage recruitment and polarization towards immunosuppressive macrophages." (PMID 38022603, 2023). "In preclinical tumor models, improved effects were observed when CSF1/CSF-1R blockade was combined with irradiation, paclitaxel, anti-VEGFR antibody, and ICB." (PMID 37415162, 2023). "The stiffness of the ECM supports the release of chemoattractants like CCL2 and colony-stimulating factor-1 (CSF-1) from CAFs and tumor cells." (PMID 36793444, 2023). "Our model accounts for macrophage extravasation in response to tumour-derived CSF-1, their subsequent tumour infiltration, and the CSF-1/EGF paracrine loop that mediates cross-talk between tumour cells and macrophages." (PMID 36972297, 2023). "The blocking of the CSF1/CSF1R axis by targeting CSF1 or CSF1R is in clinical trials to eliminate the tumor-promoting macrophage population." (PMID 37279073, 2023). "In this context, tumor cells release colony-stimulating factor 1, while TAMs release epithelial growth factor (EGF)." (PMID 38201623, 2023). "In another example, CCL8 produced by TAMs also upregulate tumor cell secretion of colony stimulating factor 1 (CSF-1) which is crucial to macrophage and DC survival and differentiation through signaling via CSF-1R." (PMID 37114134, 2023). "Secondly, Mφ-SDNPs can scavenge CCL2 and CSF1 in the tumor site and exploit the SIRPα-CD47 interaction to remodel the tumor microenvironment." (PMID 38111068, 2023). "Overall, this data highlights the significance of CSF1 as a key regulator of the tumor microenvironment and as a promoter of the EMT process." (PMID 37505292, 2023). "Nonetheless, CSF1 is also a major chemoattractant that regulates the production, survival, and recruitment of TAMs to the tumor microenvironment." (PMID 37505292, 2023). "In brief, anti-tumour macrophages extravasate from blood vessels and migrate towards clusters of tumour cells, in response to tumour-derived signals such as colony stimulating factor-1 (CSF-1)." (PMID 36972297, 2023). "To conclude, our findings highlight the therapeutic potential of combining CSF1/CSF1R pathway targeting agents with neoepitope targeting vaccines to further modulate anti-tumor immune responses in the tumor microenvironment." (PMID 37505292, 2023). "Neutralization of CSF1R or CSF1 has been shown to inhibit tumor growth in a variety of tumor types by inhibiting the proliferation of intratumor macrophages." (PMID 36969873, 2023). "In particular, the attack of tumor cells by chemotherapy-induced stimulation of tumor-derived CSF1 release, followed by an increase in TAM infiltration, provides the tumor with additional growth and survival factors." (PMID 37504287, 2023). "CSF-1 is another cytokine that allows the recruitment of TAMs to the tumor and several therapeutic strategies aiming at blocking the activation of the CSF-1/CSF1R pathway are currently investigated." (PMID 37143666, 2023). "In particular, as we vary model parameters associated with the rate of macrophage extravasation and their chemotactic sensitivity to CSF-1, we observe tumour Elimination, Escape, and Equilibrium." (PMID 36972297, 2023). "In many tumors, CSF1 and its receptor CSF-1R are highly expressed, and inhibition of migration and infiltration of tumor tissue can be observed after inhibiting CSF1." (PMID 37773794, 2023). "We conclude that MYC is sufficient to regulate the CSF1 expression in the OS tumor, which orchestrates the migration of macrophages in the TME of OS." (PMID 37279073, 2023).